BRCA2 (BRCA2 DNA repair associated)
Diseases named in the same sentence as BRCA2 in open-access papers (continued):
Sharing a sentence is not in itself a finding about the gene and the disease.
breast cancer (continued). "Promoter hypomethylation in PALB2, a breast cancer susceptibility gene that localizes the BRCA2 gene at the site of DNA damage, has been established as a biomarker for sporadic breast cancer." (PMID 34576196, 2021). "On average, 10–15% of women diagnosed with breast cancer before 35 years are carriers of pathogenic variants in BRCA1 or BRCA2." (PMID 34529195, 2021). "None of the PRS showed significant associations with ER-negative contralateral breast cancer for BRCA2 heterozygotes, but the ER-negative PRS313 exhibited the largest HR estimate, HR per SD = 1.10, 95% CI (0.91–1.32), p value = 0.346." (PMID 34113011, 2021). "Carriers with pathogenic variants in BRCA1 or BRCA2 were also more likely to have a family history of breast cancer than carriers of pathogenic variants in the other genes (p < 0.0001)." (PMID 34887416, 2021). "Another integration of different analysis sources is the pathogenic heterozygous variant for BRCA2 p.Lys1638Ter observed in Mother and her >1SD genetic risk observed for breast cancer." (PMID 33763108, 2021). "In Caribbean-born women and men with breast cancer, having a first- or second-degree family member with breast cancer was associated with having any BRCA1 or BRCA2 germline variant (odds ratio, 1.58; 95% CI, 1.24-2.01; P < .001)." (PMID 33646313, 2021). "In the present study, 6 Tunisian breast cancer patients harbor two pathogenic mutations on the same allele of BRCA2 (c." (PMID 34456966, 2021). "The goal of our study was to assess the associations of various treatments in reducing breast-cancer mortality in the BRCA2 patient population." (PMID 33597716, 2021). "Mutations in the BRCA2 are known to be associated with increased risk of several cancer types, including pancreatic cancer." (PMID 33968986, 2021). "We identified 664 women with stage I–III breast cancer and a BRCA2 mutation by combining five different datasets (retrospective and prospective)." (PMID 33597716, 2021). "In this paper, we aim to study the prevalence and pattern of germline BRCA1 and BRCA2 mutations among a group of young Jordanian patients with breast cancer thought to be at higher risk for such mutations." (PMID 34290354, 2021). "PR status was significantly different between BRCA1 and BRCA2 mutation carriers; BRCA2 carriers are more likely to develop progesterone receptor (PR) positive tumors and PR-negative breast cancer are associated with BRCA1 mutation carriers (p=0.000084)." (PMID 34490083, 2021). "Further studies showed that males who harbored a germline BRCA1 and BRCA2 mutation, identified via a family history of breast cancer, were reported to have an increased the risk of PCa by three-fold and seven-fold, respectively." (PMID 34830851, 2021). "Specifically, mutations in FANCD1 (also called BRCA2) have an 82% lifetime risk of breast cancer, and a 23% risk of ovarian cancer." (PMID 34884777, 2021). "Two to three percent of breast cancer patients harbor germline mutation of either BRCA1 or BRCA2 genes." (PMID 34439286, 2021). "For BRCA2 mutations, the chance of developing breast cancer is 45–49%, and for ovarian cancer it is 11–18%." (PMID 34711195, 2021). "For a woman carrying a PV of the BRCA2 gene, the lifetime risk of developing a breast and ovarian cancer is about 66 and 12%, respectively, and the risk of developing contralateral breast cancer is about 12% in the 5 years from the initial diagnosis." (PMID 34572941, 2021). "For BRCA1, BRCA2, and other genes associated with breast cancer, there is also an impact of population ancestry and potential modifier alleles." (PMID 34584094, 2021). "Among BRCA mutations identified in breast cancer patients, BRCA1_c.211dupA, BRCA1_c.5266dupC, BRCA2_c.-227-?_7805+?, BRCA2_1310_1313delAAGA, BRCA2_c.1389_1390delAG and BRCA2_c.7654dupA occurred in BCCRs." (PMID 34490083, 2021). "Approximately 15-20% of familial breast cancer cases are attributed to the BRCA1 or BRCA2 gene mutations." (PMID 34710987, 2021).
breast cancer (continued). "Another aspect is that BRCA2 999del5 mutation carriers with breast cancer have been associated with a significantly worse prognosis than non-carriers." (PMID 35052422, 2021). "BRCA1/BRCA2 mutations account for the majority of hereditary breast cancers, representing about 5–7% of all unselected breast cancers." (PMID 33808562, 2021). "Regarding genetics, approximately 10% of male breast cancer patients have BRCA2 mutations, and <1% are accompanied by BRCA1 mutations." (PMID 33725931, 2021). "So far, more than 1800 distinct BRCA1 and 2000 BRCA2 mutations have been reported in the Breast Cancer Information Core (BIC) database." (PMID 34490083, 2021). "In support of this conjecture, melphalan was shown to be selectively toxic to BRCA2-deficient breast cancer cell lines and to produce a longer relapse-free survival in mice than platinum or olaparib." (PMID 34367999, 2021). "It was discovered that a ‘999del5′ mutation in the BRCA2 gene explains a substantial proportion of familial risk of breast cancer in Iceland." (PMID 34830851, 2021). "Pathogenic mutations in the BRCA1 and BRCA2 genes confer high risks of breast, ovarian, and contralateral breast cancer (CBC)." (PMID 34575624, 2021). "Germline alterations resulting in cancer predisposition - for example BRCA1 and BRCA2 variants - increase the risk of breast cancer in humans, and alterations in these genes have also been documented in dogs with mammary tumors." (PMID 33834049, 2021). "Despite their importance as the major genetic risk factors for breast cancer, pathogenic variants in BRCA1 and BRCA2 account for only ~20% of familial breast cancer risk." (PMID 34439109, 2021). "Women who carry inherited pathogenic mutations in the BRCA1 or BRCA2 genes possess an increased risk of developing breast cancer (BC) and ovarian cancer (OC) compared to women of the general population without these mutations." (PMID 34090422, 2021). "We sought to estimate the impact of bilateral oophorectomy and other treatments on breast cancer-specific survival among patients with a germline BRCA2 mutation." (PMID 33597716, 2021). "Referral for the group of younger patients is important because young age at diagnosis of breast cancer indicates a higher risk to carry a BRCA1 or BRCA2 pathogenic variant and is a clear indication for referral to breast cancer genetic testing." (PMID 33933926, 2021). "As reported by the group from Aviano, our analysis also suggest possible genotype–phenotype correlation between the BRCA2:c.7806-2A > G variant and predisposition to male breast cancer compared to other deleterious BRCA2 variants identified at our Institute." (PMID 33891299, 2021). "Women who inherit a deleterious germline BRCA1 or BRCA2 mutation face high lifetime risks of developing breast cancer by the age of 80, which are estimated to be 72% and 69%, respectively." (PMID 34828379, 2021). "Since the mid-1990, extensive efforts have been dedicated to the analysis of BRCA1 and BRCA2, the two most commonly mutated breast cancer genes." (PMID 34456966, 2021). "In Iceland, a BRCA2 999del5 truncation mutation in exon 9 was isolated in a family with several cases of male and female breast cancer." (PMID 35052422, 2021). "PALB2 encodes a protein that interacts with BRCA2 to execute double-stranded DNA repair through homologous recombination (HR) and was identified as a breast cancer predisposition gene in 2007." (PMID 33854214, 2021). "Among the identified mutations c.211dupA, c.5266dupC in BRCA1 and c.1310_1313delAAGA in BRCA2 were the most recurrent mutations encountered among the hereditary breast cancer cases." (PMID 34490083, 2021). "Research has provided evidences that in BRCA1 and BRCA2 mutation carriers peak breast cancer onset is approximately at 30-40 and 40-50 years of age, respectively." (PMID 33773534, 2021).
breast cancer (continued). "The tumor-suppressor genes BRCA1 and BRCA2 are the principal genes responsible for inherited cancer predisposition—40–80% of mutation carriers will develop a breast cancer in their life-time." (PMID 33917614, 2021). "Mutations in breast cancer type 1 susceptibility protein (BRCA1) and BRCA2 genes are associated with a high risk of SPM for breast cancer or ovarian cancer." (PMID 34395291, 2021). "The prevalence of BRCA2 mutations in men with breast cancer ranges from 4 to 40% in different populations." (PMID 34461861, 2021). "It is predestined that 5- 10 % of breast cancer cases are caused by inherited mutations such as those in the BRCA1 and BRCA2 breast cancer allergy genes." (PMID 34710987, 2021). "The association of germline BRCA1 and BRCA2 PGVs with high-risk breast cancer predisposition has been well recognized and clinical diagnostic testing of these genes has been offered for the past 23 years in Manchester." (PMID 34113003, 2021). "The variant, BRCA2 c.5645C>A has been reported in breast cancer patients from Japan, China, and the Czech Republic, and in prostate cancer patients." (PMID 34287479, 2021). "BRCA1 and BRCA2 mutant genes predispose individuals to an elevated risk of breast cancer, and those with a family history of cancer are recommended to undergo gene detection based on the National Comprehensive Cancer Network (NCCN) guidelines." (PMID 33549054, 2021). "BRCA1 has a large risk-reduction effect on ovarian cancer, whereas BRCA2 has a risk-reduction effect on breast cancer after RRSO." (PMID 32862296, 2021). "One also sees that somatic mutations of BRCA1 or BRCA2 associate with additional up-regulated spots compared to their germline counterparts (for example compare gBRCA1 and sBRCA1 portraits for breast cancer, or gBRCA2 vs. sBRCA2 portraits for ovarian cancer)." (PMID 33525353, 2021). "Here, the authors perform a case-only genome-wide association study and highlight novel loci associated with breast cancer risk for BRCA1/BRCA2 mutation carriers." (PMID 33597508, 2021). "Deleterious variants in BRCA1 or BRCA2, either germline or somatic, are most frequently observed in ovarian cancer (13.8%), castrate-resistant prostate cancer (11.8%), and breast cancer (6.8%), but can occur in many other cancer types as well." (PMID 34067105, 2021). "Although BRCA1 and BRCA2 are the most well-known risk genes associated with about a 20-fold increased breast cancer risk, they only account for 20% of familial breast cancer due to the low frequency of mutations." (PMID 34069208, 2021). "Consistent with our findings, various previous studies reported that there is a much higher rate of TNBC among BRCA1 mutation carriers and BRCA2-related breast cancer is often luminal." (PMID 34490083, 2021). "In a previous study comparing Chinese and Malay breast cancer patients, a higher prevalence of BRCA2 mutations was found among Malay breast cancer patients." (PMID 34857041, 2021). "During the last decade, BRCA1 and BRCA2 mutations (BRCA1/2) have been screened for hereditary breast cancer and results showed that mutations in BRCA1/2 account for 5% of hereditary breast cancer." (PMID 33402103, 2021). "Our previous studies demonstrated that mutation and downregulation of BRCA2 were both associated with canine mammary tumors." (PMID 33407082, 2021). "BRCA1-related breast cancer is often associated with triple negative breast cancer (TNBC) subtype, whereas BRCA2-associated tumors tend to be luminal-like breast cancer." (PMID 34202525, 2021). "Accordingly, a recent nested case-control study conducted in the USA revealed that only 1.18% of the unselected postmenopausal breast cancer patients were BRCA1/BRCA2 mutation carriers." (PMID 34287479, 2021). "On the contrary, carriers of BRCA2 mutation are more prone to develop ER- or PR-positive breast cancer." (PMID 33540843, 2021).
breast cancer (continued). "According to a previous study, about half of the cases of early-onset breast cancer are due to different inherited mutations in the BRCA2 gene." (PMID 34367235, 2021). "Common to the two studies is the VUS BRCA2-T207A, an unclassified missense variant identified in breast cancer patients." (PMID 34359619, 2021). "Overall, in this study, developed fuzzy logic and neural networks models were found to be successful in predicting correct risk scores for BRCA1 and BRCA2 associated breast cancers, especially classifying VUS variants." (PMID 34828379, 2021). "BRCA2 mutations are found in 4% to 40% of male breast cancer patients compared with 5–10% of female patients with hereditary breast cancer." (PMID 33725931, 2021). "In three of the BRCA2 c.7934delG carriers a high-risk MammaPrint 70-gene profile was noted, indicating a significantly increased risk for both secondary cancers and breast cancer recurrence." (PMID 34660253, 2021). "BRCA1 and BRCA2 mutations put individuals at higher risk for developing certain malignancies, particularly ovarian and breast cancer." (PMID 34711195, 2021). "Partner and Localizer of BRCA2 (PALB2) is a caretaker gene implicated in both BRCA1/2 breast cancer and Fanconi’s Anemia (FA) in the event of monoallelic and biallelic loss-of-function mutations, respectively." (PMID 34070674, 2021). "Fifty-five to sixty-five percent of women with BRCA1 mutation and 45% of women with BRCA2 mutations will develop breast cancer by the age of 70 years." (PMID 33578759, 2021). "Differential gene expression analysis showed only subtle variation between germline and somatic mutations for BRCA1 and BRCA2 genes in ovarian and breast cancers." (PMID 33525353, 2021). "In previously published data, breast cancer risk was mildly elevated in BRCA2 c.9976A>T carriers when compared to control populations in three reports." (PMID 33672545, 2021). "Since their discovery over three decades ago, the breast cancer 1 (BRCA1) and 2 (BRCA2) genes remain the most clinically significant breast cancer predisposition genes." (PMID 34771713, 2021). "BRCA1 and BRCA2 mutations are most prevalent in hereditary breast cancer and are associated with increased risk of breast and ovarian cancer." (PMID 34439348, 2021). "This study evaluates the prevalence of germline mutations in BRCA1 and BRCA2 among breast cancer patients diagnosed at age 40 or younger in Jordan." (PMID 34290354, 2021). "Variant p.Leu1669Ter in BRCA2 was also seen in two sisters with breast cancer at ages 26 and 56; it was also seen in an 81-year-old female." (PMID 33558524, 2021). "A recent study on our cohort showed that women with the BRCA2 999del5 germline mutation and relative short telomere length measured in blood cells were at significantly higher risk of being diagnosed with breast cancer." (PMID 35052422, 2021). "The current study provides insights into the potential mechanisms by which excess body fat increases breast cancer penetrance in women with BRCA1 or BRCA2 mutations, including in pre-menopausal women." (PMID 33649363, 2021). "Germ-line mutation in BRCA (BReast CAncer gene) 1 or BRCA2 are found in 3–4% of all women with breast cancer." (PMID 33996049, 2021). "In particular, BRCA1 and BRCA2 mutation carriers have a 60–65% and 45–55% risk of breast cancer up to the age of 70 years, respectively." (PMID 34575624, 2021). "Around 10%–20% of EOBC cases are hereditary BRCA1 and BRCA2 are the most common mutated genes related to breast cancer since their discovery in the early 1990s." (PMID 33807872, 2021).
breast cancer (continued). "On the contrary, in ovarian cancer, the expression of BRCA1 was the lowest in samples with somatic BRCA1 mutations compared to other groups, while the expression of BRCA2 expression showed a similar pattern as in breast cancer." (PMID 33525353, 2021). "Telomere length was shown to be a modifier of breast cancer risk in BRCA2 999del5 mutation carriers in the same study." (PMID 35052422, 2021). "Here we report the case of a patient with pathogenic germline BRCA2-driven breast cancer who acquired resistance to the PARP inhibitor olaparib." (PMID 33619265, 2021). "The combination of everolimus (mTOR inhibitor) and olaparib (PARPi) has been tested in BRCA2-mutated breast cancer patient-derived xenografts (PDX) with promising results." (PMID 34572083, 2021). "BRCA1 and BRCA2 mutation play an important role in genetic susceptibility of breast cancer progression." (PMID 33968766, 2021). "EMT-like phenotype correlated with a high expression of the ABCB1B gene and was associated with multidrug resistance also in BRCA2-deficient sarcomatoid mammary tumors." (PMID 33540843, 2021). "An example of this is the FDA approved application of PARP inhibitors to treat breast cancer patients with a BRCA1 or BRCA2 mutation." (PMID 34615983, 2021). "Other breast cancer susceptibility genes that have equivalent information include BRCA2 (penetrance to age 70, 45% (95% CI, 31–56%), PALB2 (penetrance to age 70, 44% (95% CI, 37–52%) and BRCA1 (penetrance to age 70, 65% (95% CI, 44–78%)." (PMID 33803639, 2021). "Generally, women who harbor BRCA1/BRCA2 mutations are more frequently diagnosed with breast cancer at an early age (≤40 years) or with ovarian cancer at any age." (PMID 34287479, 2021). "Our study indicates that 10.6% of the breast cancer patients with at least one close relative affected by the disease (until third degree) harbor germline BRCA1/BRCA2 mutations." (PMID 34287479, 2021). "By focusing on three specific rare missense variants identified in breast cancer patients, in this review, we discuss how the functional evaluation of this type of variants can be used to reveal novel activities of BRCA2." (PMID 34359619, 2021). "Patients with a germline mutation in the breast cancer susceptibility genes Breast cancer 1 (BRCA1) or Breast cancer 2 (BRCA2) have a high risk of developing breast cancer or ovarian cancer and show high sensitivity to these DNA damaging agents." (PMID 33670893, 2021). "Hereditary breast cancer accounts for up to 5–10% of all breast cancers with two high-penetrance genes (BRCA1 and BRCA2) responsible for about 16% of the familial risk of breast cancers, associated with a 60–80% lifetime risk of developing breast cancer." (PMID 32725533, 2021). "Our results indicate a possible association between this variant and higher risk of breast cancer in males compared to other identified P/LPVs in BRCA2." (PMID 33891299, 2021). "Further studies in BRCA2 or ATM deficient ovarian cancer or breast cancer models will be required to confirm our preliminary observations." (PMID 34373746, 2021). "By the age of 70 years, BRCA1 and BRCA2 carriers were previously found to have average cumulative risk of contralateral breast cancer of 83% and 62%, respectively." (PMID 34206661, 2021). "As previously suggested by the group of researchers from Aviano, our results also indicate a possible association between this splice-site BRCA2 variant and higher risk of breast cancer in males compared to other identified P/LPVs in BRCA2 gene." (PMID 33891299, 2021). "These samples included tumour tissue from 151 BRCA1-associated and 124 BRCA2-associated breast cancer cases." (PMID 34287743, 2021). "The BRCA1 and BRCA2 genes are mutated in 5–6% of breast cancers and 16% and 6% of ovarian cancers, respectively." (PMID 34316706, 2021). "Other than BRCA1 and BRCA2, inherited mutations in about a dozen other genes are also associated with increased breast cancer risk." (PMID 33893322, 2021).